CD4 (CD4 molecule)
Diseases named in the same sentence as CD4 in open-access papers (continued):
Sharing a sentence is not in itself a finding about the gene and the disease.
AIDS (continued). "The influence of TCM on the CD4+ T-cell count of patients with HIV/AIDS might be significantly related to the CD4+ T-cell count at the time of initial treatment." (PMID 34326884, 2021). "The mean CD4 count for patients with AIDS was 128.65 ± 104.56 cells/μl." (PMID 34476236, 2021). "Discontinuation of the treatment may result in AIDS and lead to poor recovery of the CD4+ T-cell population, even after reimplementation of antiretroviral therapy and a decrease in viral load." (PMID 33924043, 2021). "A large proportion of PLWH in our cohort had prior AIDS defining events or CD4+ nadir lower than 200 cells/μL and altered coagulation could be due to legacy effects of severe immunodeficiency." (PMID 33623050, 2021). "CD4+ T cell counts circulating in the blood are less than 200 cells/μL in AIDS patients." (PMID 34344350, 2021). "As late presenters are defined patients presenting for care with a CD4 cell count below 350 cells/mm3 or with an acquired immune deficiency syndrome (AIDS)-defining event regardless of the CD4 cell count." (PMID 33526074, 2021). "HIV/AIDS disease development comprises an acute stage, after the primary infection, characterized by a high viral load which greatly increases transmissibility and a substantial decline of host CD4+ T cell counts, which can lead to the influenza-like syndrome." (PMID 33451365, 2021). "More recent evidence shows that HIV patients with early infection or in early stages (e.g., CD4 > 500 and absence of AIDS-defining infections) have the same operative risk as HIV-negative patients and should therefore be treated accordingly." (PMID 34372902, 2021). "In addition to low CD4 and male‐to‐male sex, KS risk after ART was associated with age and history of other AIDS‐defining illnesses." (PMID 33405281, 2021). "In an analysis of two AIDS Clinical Trials Group (ACTG) studies, higher levels of HIV reservoir in bulk CD4 T-cells before ART initiation were associated with higher levels while on-ART, and a similar association was observed for markers of immune activation, proliferation and inflammation." (PMID 34449812, 2021). "Gradual degradation of the adaptive immune system through targeted destruction of CD4+ T lymphocytes allows progression to the late phase of HIV disease, Acquired Immunodeficiency Syndrome (AIDS)." (PMID 34290739, 2021). "Compared to HIV-1, HIV-2 infection may have a longer asymptomatic latency period, low levels of plasmaviremia, higher CD4 T cell counts, slower CD4+ T cell exhaustion, and slower progression to AIDS." (PMID 34832533, 2021). "Lower CD4 counts refer to a higher risk of death caused by AIDS-related diseases, liver-related diseases, non-AIDS infections and non-AIDS-defining malignancies." (PMID 34886257, 2021). "LP was defined as HIV diagnosis with CD4 count ≤350 cells/μL or an AIDS defining event (ADE)." (PMID 33882093, 2021). "Our finding showed that that male sex, MSM, CD4 count < 200 cells/mm3, no AIDS history and not receiving ART were significant risk factors for HZ among HIV infected patients." (PMID 34070645, 2021). "CD4 Lymphocyte Count (CD4) is a major predictor of HIV progression to AIDS." (PMID 33766121, 2021). "There are two important primary screenings to evaluate HIV/AIDS treatment: CD4 and viral load." (PMID 33509063, 2021). "The appearance of HCMV retinitis during AIDS is no exception with retinal disease and subsequent vision loss commencing when CD4+ T-cell numbers become substantially low, i.e., below 50 CD4+ T cells per microliter of peripheral blood." (PMID 34358000, 2021). "A diagnosis of histoplasmosis was the AIDS-revealing condition in 52% of our PLWH and was associated with severe immunodepression as confirmed by the very low median CD4+ cell count and the observation of concomitant opportunistic infections in nearly 30% of the patients." (PMID 34198597, 2021).
AIDS (continued). "HIV/AIDS depletes CD4+ T cells increasing TB susceptibility and severity, although it is not known about the relative importance of HIV immune suppression versus CD4+ T-cell decline." (PMID 33732233, 2021). "Being male, older, having a low educational level, and not being married were risk factors for AIDS-related mortality in both high and low CD4+ cell count groups." (PMID 34592916, 2021). "TCM could increase the CD4+ T-cell count among patients with HIV/AIDS who had a baseline CD4+ T-cell count of <350 cells/mL." (PMID 34326884, 2021). "We examined incidence over time that accounted for temporal changes in patient demographics (age, sex/sexual risk factor for HIV transmission, cohort site) and clinical characteristics at clinic entry (CD4 cell count and history of other AIDS‐defining illness) using multivariable models." (PMID 33405281, 2021). "Comparison of surgical characteristics of HIV/AIDS patients with different CD4." (PMID 34616598, 2021). "When CD4+ cell counts decline below a certain level, HIV-infected individuals are at risk of immune deficiency and more susceptible to infection, resulting in progress to AIDS or death." (PMID 34592916, 2021). "In contrast, AIDS is typically defined through a CD4 count of less than 200 cells/mL." (PMID 34094761, 2021). "In this study, the high rate of cryptococcal antigenemia was observed among hospitalized HIV/AIDS patients, and it is alarming and highlights the need for improving CD4 status, expanding serum cryptococcal antigen screening, and strengthening regular cryptococcal antigenemia surveillance systems." (PMID 33531906, 2021). "Age, work status, CD4 at time of diagnosis, current CD4 level, duration of treatment, WHO clinical stage at treatment initiation, and taking Cotrimoxazole prophylaxis were associated with HRQoL among people living with HIV/AIDS on HAART." (PMID 33667245, 2021). "The attrition rate is less among patients with low CD4 cell count, possibly because patients with lower CD4 cell counts are more likely to have AIDS symptoms; such individuals may have better compliance to ART." (PMID 33628803, 2021). "It has been suggested that a persistently low CD4:CD8 ratio during long-term effective antiretroviral therapy in HIV-infected patients represents persistent immune dysfunction, which predicts a high risk of non-AIDS morbidity and mortality." (PMID 33820568, 2021). "Further studies are needed to evaluate the potential increased burden of non-AIDS comorbidities that are linked to elevated inflammatory and fungal translocation markers as a result of the policy of HIV treatment at CD4 count < 200 cells/cm3 implemented for over a decade in Tanzania." (PMID 34446039, 2021). "Indeed, CD4 T cell numbers in some GBM patients approach lows seen in patients with acquired immunodeficiency syndrome (AIDS)." (PMID 34778089, 2021). "Lower CD4 cell count, higher serum TRUST titer, HIV transmitted by heterosexual contact, not received ART, and untreated with syphilis, were associated with neurosyphilis among HIV/AIDS patients with syphilis." (PMID 34678871, 2021). "Chronic immune activation is a key driving force for CD4+ T cell depletion and progression to AIDS." (PMID 32194543, 2020). "However, it should be noted that in the context of severe AIDS (generally <50 CD4+ T cells/μL in humans), HCMV-specific CTLs can become dysfunctional, presumably due to inadequate CD4+ T cell help." (PMID 32922404, 2020). "Alternatively, a protective role might be attributed to inflammatory monocytes (defining here CD16+ monocytes) against the progression of HIV-2 infection toward AIDS, i.e., in terms of viral loads or CD4 T cell counts." (PMID 32903610, 2020). "This combination of observations led us to the hypothesis that enhancement of inflammasome-dependent, IL18-driven production of IFN-γ by non-CD4 cells may be a route to control acute toxoplasmosis in AIDS." (PMID 32753607, 2020).
AIDS (continued). "This study demonstrated that over two thirds of older adults have AIDS, as defined by CD4 count or AIDS defining illness, at the time of diagnosis, and that older patients may be less likely to achieve HIV virologic suppression at 12 weeks." (PMID 33129258, 2020). "Our narrative synthesis revealed that actors such as being male, Cigarette smoking, Khat chewing, family history of alcohol use, missing ART medication, mental distress, low CD4 count, and low income were some of the associated factors with AUD in people with HIV AIDS in Africa." (PMID 32831129, 2020). "Of the AIDS patients, the male to female ratio was 6.4:1, the average age was 46.1 ± 13.0 years (range: 11–76 years), the median CD4+ T cell count at admission was 63.5 (IQR: 18.0–165.0) cells/μl; and the average length of hospital stay was 21.7 ± 12.4 days (range: 1–75 days)." (PMID 32867780, 2020). "Using 200 CD4 cells/μl as cutoff for AIDS diagnosis, we had 6 AIDS patients in this study." (PMID 32678115, 2020). "This study revealed that CD4+ T-cell count <200cells/μl, unavailability of a latrine, and history of diarrhea were the significant risk factors of intestinal parasitic infections for people who are living with HIV/AIDS in Ethiopia." (PMID 33382867, 2020). "It was also revealed that WHO clinical AIDS staging three and four, CD4 cell count <200 cells/mm3, functional status, patient marital status and access to water supply were significantly associated with undernutrition among adult HIV/AIDS patients." (PMID 32163485, 2020). "Although a decreased systemic CD4/CD8 T cell ratio has also been associated with increased human atherosclerosis, this phenomenon has been observed primarily in persons living with HIV/AIDS." (PMID 33391278, 2020). "In the setting of untreated chronic HIV infection, CD4/CD8 ratio predicts time to AIDS development." (PMID 32258852, 2020). "This study aims to make use of a longitudinal data modelling approach to analyze data on the number of CD4+cell counts measured repeatedly in HIV-1 Subtype C infected women enrolled in the Acute Infection Study of the Centre for the AIDS Programme of Research in South Africa." (PMID 34394215, 2020). "The depletion of memory CD4+ T cells preceding the manifestation of AIDS may be mainly due to HIV infection of these cells." (PMID 32154191, 2020). "The US President’s Emergency Plan for AIDS Relief, which provides substantial funding for AIDS treatment, care and prevention in countries most affected by the epidemic, has progressively reduced its support for CD4 testing." (PMID 32414825, 2020). "Risk of MTCT may be affected by many factors, including high maternal viral load, lower CD4 count of the mother, mother with AIDS defining disease, premature rupture of the amniotic membrane, preterm delivery and breastfeeding." (PMID 31564083, 2020). "HIV/AIDS patients with low number of CD4 normally develop opportunistic infections." (PMID 32126572, 2020). "Infection by human immunodeficiency virus (HIV; family of Retroviridae, ssRNA) leads to acquired immunodeficiency syndrome (AIDS), an immunodeficiency characterized by a severe reduction of CD4 T‐cells." (PMID 31777064, 2020). "It was developed for monitoring human immunodeficiency virus (HIV)/acquired immunodeficiency syndrome (AIDS) progression and can detect CD4 (cluster of differentiation 4) + T-lymphocytes in human blood." (PMID 32182878, 2020). "We found that serious NADEs were also another major complications in AIDS patients prior to receiving cART besides AIDS-defining events, and serious NADEs could occur among cART-naive AIDS patients with older age or lower CD4 categories." (PMID 33351812, 2020). "Some studies also argue that CD4 cell count predicts clinical information (event time data) whereas HIV viral load trajectories largely determine the time from initial infection to AIDS: high initial viral load is a marker for rapid progression." (PMID 32216755, 2020).
AIDS (continued). "Initiation of antiretroviral therapy (ART) regardless of CD4+ count reduces the risk of AIDS and non-AIDS-related morbidity and mortality in patients with HIV-1 infection." (PMID 32687492, 2020). "CD4 + cell count is used as a prognostic marker of HIV/AIDS disease progression." (PMID 33051567, 2020). "Although other clinical measures were not recorded, literatures would suggest that improved CD4 cell counts would make the individuals less susceptible to opportunistic infections and have a lower risk of progression to AIDS and death." (PMID 33228562, 2020). "But the analysis of their functions led to understanding that the differences in the expression of these proteins in the CD4+ or CD8+ T cells and some other immune cells may be associated with the velocity of HIV/AIDS progression." (PMID 33414815, 2020). "CD4+% has been proposed as another independent predictive factor of AIDS progression." (PMID 31945066, 2020). "In addition to that, among the determinants of the progression of HIV/AIDS, both the CD4 cell counts and viral load counts are included in the same model." (PMID 32228523, 2020). "Distinct microbial communities in the digestive tract of HIV-infected individuals under antiretroviral therapy (ART) can be found; furthermore, patients with a history of AIDS, displaying T CD4+ lymphocytes count < 200 cells/mm3, have significantly lower subgingival plaque fungal diversity." (PMID 32944157, 2020). "The existence of non-pathogenic simian immunodeficiency virus strains, which do not cause gradual depletion of CD4 T cells and progression to AIDS in their natural hosts, confirms this view." (PMID 33142907, 2020). "In our systematic review, all the AIDS patients’ CD4+ lymphocyte count was below 100 cells/mm3." (PMID 32523970, 2020). "The results in our study revealed that serious NADEs could occur in cART-naive AIDS patients with different CD4 levels, especially with CD4 ≤ 350 cells/ul, which was consistent with results previously found in industrialize countries." (PMID 33351812, 2020). "Some limitations of our study include a lack of detailed information on non-AIDS events, which meant that we were unable to assess the association between the CD4+:CD8+ T cell ratio and non-AIDS events." (PMID 32664736, 2020). "This phenomenon is of clinical relevance because the persistently low CD4 T cell counts are associated with a high risk of disease progression, AIDS and non-AIDS clinical events and death." (PMID 30921390, 2019). "Human immunodeficiency virus (HIV) infects the immune system’s CD4+ T cells, inducing chronic inflammation that drives the progression into acquired immune deficiency syndrome (AIDS) (HIV/AIDS, 2019: The Basics Understanding HIV/AIDS)." (PMID 32038528, 2019). "AIDS-induced parkinsonism usually occurs when CD4+ T cell counts are very low." (PMID 31396143, 2019). "In AIDS patients, although the viral loads in peripheral blood can be kept under control after antiretroviral therapy, their health conditions can still deteriorate with dramatically decreased CD4+ T-cell count." (PMID 31165736, 2019). "Phenotyping of lymphocytes using flow cytometry is extensively used for enumeration of the CD4 absolute cell counts to determine HIV-infection or AIDS disease status, for monitoring disease progression or co-infections, for patient staging, and for initiation of anti-retroviral treatment (ART)." (PMID 30689658, 2019). "The median time to AIDS from the first recorded CD4% value was 9.4 years (95% CI, 6.7 to 12.1 years) for faster progressors with a low CD4% level and 15.5 years (95% CI, 14.3 to 16.6 years) in slower progressors with a high CD4% level (P < 0.001 [log rank test])." (PMID 30622192, 2019). "CD4 count < 350 cells/μL predicted hrHPV persistence, while prior AIDS predicted ≥HSIL." (PMID 31438877, 2019).
AIDS (continued). "This study showed that patients in WHO stage II and III were negatively associated with increment in the recent CD-4 count compared with the WHO stage I. Different other studies have also shown that WHO clinical stage and classification of HIV/AIDS correlates well with CD4+ T-lymphocyte counts." (PMID 31830095, 2019). "In this study, with the use of ART treatment in HIV positive patients and administration of sulfamethoxazole-trimethoprim treatment during the course of AIDS for patients with CD4 T-cell counts less than 200 cells/μl, frequency of microsporidian and coccidian infection was low." (PMID 31110984, 2019). "RITA classified a diagnosis as recent based on an AI < 1.5, unless epidemiological criteria (CD4 count <200 cells/mm3; viral load <400 copies/ml; the presence of AIDS-defining illness; prior antiretroviral therapy use) indicated a potential false-recent result." (PMID 30869051, 2019). "Consequently, very high CD4 counts seemed to exhibit low malaria parasite density among people living with HIV/AIDS." (PMID 31354844, 2019). "The distribution of patients based on CD4 count was further stratified as follows: CD4 < 100cells/μL, i.e., severe immunosuppression 50% (56/112); CD4 < 200 cells/μL, i.e., AIDS 69.6% (78/112); and CD4 < 350 cells/μL, i.e., late-stage HIV disease 83.0% (93/112)." (PMID 31638941, 2019). "Persistent immune activation plays a central role in CD4+ T cell depletion and progression to AIDS and may be considered to be a predictor of disease progression in ART-naïve patients." (PMID 30665429, 2019). "One of the important factors deciding the treatment of HIV/AIDS is the CD4 count." (PMID 31781388, 2019). "Furthermore, the steady decline in numbers of CD4+ T cells in HIV infection became predictive of progression to full blown AIDS, revealing the need to longitudinally track CD4+ T cells as a biomarker of disease progression following HIV infection." (PMID 31552044, 2019). "About 15% had a history of AIDS, and the median nadir CD4 was 290 cells/mm3." (PMID 30946765, 2019). "ophthalmoscopic examination and rigorous eye check up should be a compulsory practice in every case of HIV/AIDS patients having CD4 count less than 100cells/μl and in those patients with detectable CMV viremia, even in the absence of any vision-related complaints." (PMID 31801482, 2019). "A collaborative cohort study in the United Kingdom also showed that sub-optimal CD4 increases heightened the risk of death but not new AIDS events." (PMID 30802257, 2019). "The depletion of memory CD4+ T cells preceding AIDS manifestation may be mainly due to the infection of these cells." (PMID 30862061, 2019). "Importantly, the immediate arm had fewer deaths/AIDS progressions (p = 0.035), longer time to death/AIDS progression (stratified HR = 0.53, p = 0.02), and shorter time to achieving an increase in CD4 T-cell counts to > 100/μL (11.8 versus 4.2 weeks)." (PMID 31729999, 2019). "As a result, the number of CD4 cells reduces gradually in patients with HIV/AIDS." (PMID 30875995, 2019). "Natural infection in Sooty Mangabeys and African Green Monkeys with SIVsm and SIVagm variants respectively fails to induce CD4 loss or AIDS development." (PMID 31581579, 2019). "While CRF02_AG-infected animals showed higher viremia, subtype-B-infected animals showed significantly more weight loss, lower CD4+ T-cells and lower CD4/CD8 ratios, suggesting that factors other than viremia contribute to immunosuppression and wasting syndrome in HIV/AIDS." (PMID 31337802, 2019). "Usually individuals with this low of a CD4 count are diagnosed with HIV/AIDS." (PMID 31665007, 2019). "This work is motivated by the CD4 cell count dataset from the Multicenter AIDS Cohort Study." (PMID 30450612, 2019). "In addition, it has been observed recently that a low CD4/CD8 ratio of less than 0.5 is the best predictor of non-AIDS cancer." (PMID 30755782, 2019).